GUSBP4 (GUSB pseudogene 4)
Synonyms: SMA3-L; FLJ13549; formerly C6orf216; SMAC3L; GUSBL2
Gene: Transcribed unprocessed pseudogene on chromosome 6 (57,919,784 to 57,930,291, reverse strand). Ensembl gene ENSG00000239650.
Diseases named in the same sentence as GUSBP4 in open-access papers:
GUSBP4 is named in the same sentence as 2 diseases in open-access papers, as found by Europe PMC text mining. Sharing a sentence is not in itself a finding about the gene and the disease.
GUSBP4 shares sentences with these, for which no sentence is quoted: asthma (1 paper); tumor (1).